RNU6-108P (RNA, U6 small nuclear 108, pseudogene)
Gene: Small nuclear RNA gene on chromosome 3 (57,536,252 to 57,536,358, reverse strand). Ensembl gene ENSG00000202428.
Homologues: Orthologues: chimpanzee U6 (100% identical), macaque U6 (95% identical). Paralogues in human: RNU6-43P (86% identical), RNU6-1091P (83% identical), RNU6-175P (83% identical), RNU6-97P (83% identical), RNU6-1131P (82% identical), RNU6-1141P (82% identical), RNU6-11P (82% identical), RNU6-128P (82% identical), RNU6-1340P (82% identical), RNU6-37P (82% identical), RNU6-509P (82% identical), RNU6-647P (82% identical), and 1287 more.